MTNR1B (melatonin receptor 1B)
Diseases named in the same sentence as MTNR1B in open-access papers (continued):
Sharing a sentence is not in itself a finding about the gene and the disease.
type 2 diabetes (continued). "Further evidence regarding interaction between melatonin and glucose metabolism derives from genome-wide association studies: polymorphisms in the melatonin receptor 1B gene (MTNR1B) are associated with glucose intolerance, reduced β-cell function, and a higher risk for diabetes mellitus type 2." (PMID 35140394, 2022). "The difference in effects of melatonin on oral glucose tolerance in the diabetic population may involve polymorphisms in the type 2 diabetes-associated G allele in the melatonin receptor-1B gene (MTNR1B)." (PMID 36235587, 2022). "Thus, in this study, MTNR1B rs10830963 gene was selected as a genetic marker and the effect of MTNR1B gene variant on the therapeutic efficacy of nateglinide in Chinese type 2 diabetes patients is determined." (PMID 34118937, 2021). "Moreover, in one of the cohorts, we obtained a statistically significant interaction between the MTNR1B polymorphism and the number of pregnancies, retrospectively assessed, on the type-2 diabetes risk." (PMID 33138317, 2020). "We explored whether the number of full-term pregnancies retrospectively reported by women interacted with the MTNR1B polymorphism and the later risk of type-2 diabetes." (PMID 33138317, 2020). "Interestingly, this result shows the effect of the MTNR1B-rs10830963 polymorphism on prevalent type-2 diabetes, even in an elderly population." (PMID 33138317, 2020). "Likewise, our results suggest that on analyzing the association between the MTNR1B-rs10830963 polymorphism and type-2 diabetes risk, sex-specific variables related to pregnancy in women should be considered." (PMID 33138317, 2020). "The objective of this study was to investigate whether MTNR1B gene variants influence repaglinide response in Chinese patients with newly diagnosed type 2 diabetes mellitus (T2DM)." (PMID 31787898, 2019). "Whether melatonin receptor 1B (MTNR1B) variants are associated with type 2 diabetes mellitus (T2DM) remains unclear." (PMID 30811895, 2019). "Interestingly, several polymorphisms in the MTNR1B gene are associated with type 2 diabetes, fasting glucose concentration, and insulin secretion." (PMID 28396702, 2017). "MTNR1B gene variants were reported to be a risk factor for developing type 2 diabetes." (PMID 25806809, 2015). "Because MTNR1B does increase risk of type 2 diabetes, this pattern of sustained deterioration suggests that identifying these individuals early in their glycemic progression may be beneficial in prevention efforts." (PMID 22984506, 2012). "It is interesting to note that, excluding the TCF7L2 SNP, three of the four variants most strongly associated with type 2 diabetes in the MAGIC study (MTNR1B rs10830963, PROX1 rs340874 and GCKR rs780094) have odds ratios of less than one in our South Asian populations." (PMID 21949744, 2011). "The aim of this study was to examine whether common polymorphisms in MTNR1B were associated with type 2 diabetes and related traits in a Han Chinese population." (PMID 21470412, 2011). "Whether other common variants except rs10830963 in the MTNR1B gene are associated with type 2 diabetes and fasting glucose in Han Chinese population is unknown." (PMID 21470412, 2011). "The purpose of this study was to examine whether tagging single nucleotide polymorphisms (SNPs) in the MTNR1B region were associated with type 2 diabetes and related traits in a Han Chinese population." (PMID 21470412, 2011). "In addition, we have previously reported an association for MTNR1B and type 2 diabetes in this cohort." (PMID 20161779, 2010). "Associations of MTNR1B rs10830963 with type 2 diabetes related traits in Chinese control subjects." (PMID 20628598, 2010). "MTNR1B rs10830963 was genotyped in a population-based cohort including 3,210 unrelated Chinese Hans from Beijing and Shanghai, and tested for associations with risk of type 2 diabetes, diabetes-related traits and sleep status." (PMID 20398260, 2010).
type 2 diabetes (continued). "As certain sleep disorders, such as obstructive sleep apnea, result from obesity and are associated with insulin resistance, MTNR1B could represent a new interesting candidate gene linking sleep disorders with type 2 diabetes." (PMID 19088850, 2008). "Their impact on β-cell function might represent the prevailing pathomechanism how MTNR1B variants increase the type 2 diabetes risk." (PMID 19088850, 2008). "Using our thoroughly phenotyped cohort of subjects at an increased risk for type 2 diabetes, we assessed the association of common genetic variation within the MTNR1B locus with obesity and prediabetes traits, namely impaired insulin secretion and insulin resistance." (PMID 19088850, 2008). "MTNR1A and MTNR1B are the main melatonin receptors in humans, and abnormal variants of them would trigger aberrant changes in melatonin that may contribute to the pathogenesis of type 2 diabetes." (PMID 37138267, 2023). "Thus, from the perspective of population epidemiology, this study aims to explore the association of rotating night shift work, CLOCK, MTNR1A, MTNR1B genes polymorphisms and their interactions with type 2 diabetes among steelworkers through a case–control study." (PMID 37138267, 2023). "Genetic studies suggest that variability in the MTNR1B gene is one of the factors influencing the pathophysiology of type 2 diabetes mellitus (T2DM), with the single nucleotide polymorphism rs10830963 showing the strongest association." (PMID 35733780, 2022). "The present study based on data from the UK Biobank found that both late chronotype and carrying the MTNR1B G risk allele were associated with an increased risk of type 2 diabetes (T2D)." (PMID 31623012, 2020). "Although it is known that pregnancy affects sleep quality and may disturb circadian rhythms, information about the interactive effects of the number of pregnancies on the genetic risk conferred by the MTNR1B-rs10830963 polymorphism on the future type-2 diabetes incidence is very scarce." (PMID 33138317, 2020). "Given that the sample size of our replication cohort 2 is relatively small, we undertook an exploratory analysis to study whether a greater number of pregnancies in women interacted with the MTNR1B-rs10830963 polymorphism, exacerbating the risk of future type-2 diabetes." (PMID 33138317, 2020). "Finally, we have recently shown that different genetic variants influence type 2 diabetes risk at distinct stages of the normoglycemia to IFG to type 2 diabetes progression, with MTNR1B and GCK exerting their effects preferentially in the normoglycemia to IFG transition." (PMID 22984506, 2012). "Two SNPs in melatonin receptor 1B gene, rs10830963 and rs1387153 showed significant associations with fasting plasma glucose levels and the risk of Type 2 Diabetes Mellitus (T2DM) in previous studies." (PMID 21658282, 2011). "Furthermore, nondiabetic individuals carrying the risk G-allele showed increased expression of MTNR1B in pancreatic islets and the MTNR1B risk G-allele has been suggested to increase risk of impaired fasting glycemia and type 2 diabetes through impaired insulin secretion." (PMID 20398260, 2010). "Background/Objective: The single-nucleotide polymorphism (SNP) rs10830963 in the melatonin receptor 1B (MTNR1B) gene influences insulin secretion and glucose metabolism and has been associated with an increased risk of type-2 diabetes." (PMID 40428319, 2025). "Among these, MTNR1B exhibited the highest significance (rs10830963-G, OR [95% CI] 1.57 [1.45, 1.70], p=4.42×10–29), although its effect on type 2 diabetes was modest." (PMID 38372780, 2024). "One such example is variation in MTNR1B, which implicates melatonin and its receptor in the pathogenesis of type 2 diabetes." (PMID 39011323, 2024). "The results showed that there were significant gene-environment interactions among rotating night shift work, current shift status, the duration of night shifts and MTNR1B gene rs1387153 locus on type 2 diabetes." (PMID 37138267, 2023).
type 2 diabetes (continued). "The pleiotropic locus MTNR1B (lead SNP rs4237555) was identified among type 2 diabetes (z score, −7.86; P = 3.84 × 10−15), FG (z score, −19.19; P = 4.20 × 10−82), HbA1c (z score, −7.50; P = 6.26 × 10−14), and chronotype (z score, −4.85; P = 1.22 × 10−6)." (PMID 35203577, 2022). "MTNR1B rs10830963 GG genotype is linked to increased fasting blood sugar levels, suggesting a significant relationship between melatonin, MTNR1B, and fasting blood sugar in type 2 diabetes." (PMID 32685724, 2020). "Genetic variants of the MTNR1B locus, encoding the melatonin MT2 receptor, have been associated with increased type 2 diabetes (T2D) risk." (PMID 33162895, 2020). "The maternal birth weight-associated variants at MTNR1B, GCK and TCF7L2 loci are known to be associated with fasting glucose and Type 2 diabetes susceptibility, with the glucose-raising allele associated with higher offspring birth weight." (PMID 29309628, 2018). "The reported risk alleles of genetic variants rs10830963 in MTNR1B and rs10923931 in NOTCH2 were associated with diabetes mellitus type 2-related traits in GWA studies (P<5×10−8)." (PMID 28737528, 2017). "Alleles showing the largest effects on raising birth weight through the maternal genotype (MTNR1B, GCK) are known to have relatively large effects on fasting glucose and more moderate effects on type 2 diabetes risk." (PMID 28293907, 2017). "Melatonin receptor 1B (MTNR1B) is a candidate gene for type 2 diabetes acting through elevated fasting plasma glucose (FPG)." (PMID 23402646, 2013). "The evidence that the variants GCK rs1799884, GCKR rs780094, MTNR1B rs10830963 and G6PC2 rs560887, which are related to fasting plasma glucose levels, increase the risk of type 2 diabetes mellitus (T2DM) is contradictory." (PMID 23840762, 2013). "In summary, a close link between the functional impairment of MTNR1B gene variations and type 2 diabetes has been found." (PMID 23535335, 2013). "For the GWAS-derived gene for type 2 diabetes mellitus melatonin receptor 1B (MTNR1B) it was recently shown that a number of rare to infrequent mutations can be detected in the respective patients." (PMID 23270367, 2012). "The Genome-wide Association Studies (GWAS) have provided strong supports for the associations of genetic variations in the MTNR1B locus with FPG, glucose level, insulin secretion and type 2 diabetes." (PMID 22768333, 2012). "In the GLACIER cohort, eleven loci (including the known type 2 diabetes genes TCF7L2 and SLC30A8) were nominally associated with IFG cross-sectionally, and MTNR1B and G6PC2 were also associated with development of IFG in longitudinal analyses." (PMID 22984506, 2012). "We showed that SNPs from GCK, G6PC2 and MTNR1B modulated the fasting glucose levels in the normoglycaemic population while SNPs from G6PC2 and GCKR was associated with type 2 diabetes." (PMID 20668700, 2010). "In conclusion, we showed that GCK, G6PC2 and MTNR1B variants modulated fasting glucose levels while G6PC2 and GCKR variants were associated with type 2 diabetes in the Shanghai Chinese." (PMID 20668700, 2010). "This study aimed to investigate the effects of MTNR1B rs10830963 on fasting glucose, type 2 diabetes and sleep status in Chinese Hans." (PMID 20398260, 2010). "SNPs from GCK, GCKR, G6PC2 and MTNR1B were genotyped in the Shanghai Chinese, including 3,410 type 2 diabetes patients and 3,412 controls." (PMID 20668700, 2010). "Genome-wide association studies (GWAS) in White Europeans have shown that genetic variation rs10830963 in melatonin receptor 1B gene (MTNR1B) is associated with fasting glucose and type 2 diabetes, which has also been replicated in several Asian populations." (PMID 20398260, 2010). "In this study, neither of six missense MTNR1B variants was associated with type 2 diabetes (N=8592 Danish individuals, 3617 with type 2 diabetes)." (PMID 40064676, 2025).
type 2 diabetes (continued). "The higher type 2 diabetes prevalence previously observed in carriers of missense MTNR1B variants causing impairment in MT2 signalling was not replicated in the UK Biobank, yet carriers had elevated HbA1c levels." (PMID 40064676, 2025). "Similarly, transcripts of candidate genes for type 2 diabetes (Blk, C2cd4a, C2cd4b, Cdkn2a, Hnf1a, Mtnr1b, Pou5f1, Slc30a8) and type 1 diabetes (Cd69, Il2, IL27) were not expressed in the brain." (PMID 39920851, 2025). "In addition, this study found a significant interaction between the MTNR1B gene rs1387153 locus and rotating night shift work on type 2 diabetes, which was basically consistent with the results of a laboratory study." (PMID 37138267, 2023). "Another important phenotype related to the MTNR1B-rs10830963 polymorphism is the association or not with type-2 diabetes." (PMID 33138317, 2020). "MTNR1B signalling may be a useful therapeutic target in Asian populations in the prevention of type 2 diabetes mellitus." (PMID 26196519, 2015). "Of these loci, only GCK, MTNR1B, DGKB, GCKR, ADCY5 and PROX1 (besides TCF7L2 and SLC30A8) were associated with type 2 diabetes at genome-wide significance levels, with several others (but not all) showing a consistent trend but not meeting the same stringent statistical threshold." (PMID 22984506, 2012). "Another study replicated the effects of MTNR1B rs10830963 on fasting glucose and type 2 diabetes." (PMID 20668700, 2010). "Baseline characteristics of different genotypes of MTNR1B rs1387153 in 300 patients with type 2 diabetes mellitus (T2DM) before treatment with repaglinide." (PMID 31787898, 2019). "Baseline characteristics of different genotypes of MTNR1B rs10830963 in 300 patients with type 2 diabetes mellitus (T2DM) before treatment with repaglinide." (PMID 31787898, 2019). "The associations of MTNR1B rs3781637 with type 2 diabetes and lipids levels found in our study were not reported in the previous studies, and the function of rs3781637 is unknown." (PMID 21470412, 2011). "This receptor also exerts an inhibitory influence on insulin secretion and previous studies have linked the lead SNP (rs10830963) located in the intron of the MTNR1B gene to FPG levels, HbA1c measurements, type 2 diabetes and birth weight." (PMID 38372780, 2024). "The loci identified in the GD GWAS also included known genes affecting both type 2 diabetes and GD—GCKR, MTNR1B, and TCF7L2, as well as the MHC region." (PMID 36553520, 2022). "For instance, the role of MTNR1A and MTNR1B, THADA, CAPN10, and PPAR-γ2 in pathology of type 2 diabetes and obesity has been confirmed." (PMID 34949963, 2021). "Therefore, the MTNR1B gene might be involved in glucose homeostasis and type 2 diabetes." (PMID 21470412, 2011). "Despite these similarities, a much greater effect size for MTNR1B in GDM compared to type 2 diabetes and association of HKDC1, which encodes a hexokinase, with GDM but not type 2 diabetes suggest some differences in the genetic architecture of GDM." (PMID 37047019, 2023). "Melatonin receptor 1B (MT1B), AIS, glucose metabolism and type 2 diabetes." (PMID 19878575, 2009). "The birth weight-raising maternal alleles at the identified loci (MTNR1B, GCK and TCF7L2) are strongly associated with higher fasting glucose and Type 2 diabetes in non-pregnant adults, and with glycemic traits and gestational diabetes mellitus in pregnant women." (PMID 29309628, 2018). "Previous studies identified melatonin receptor 1B (MTNR1B), islet-specific glucose 6 phosphatase catalytic subunit-related protein (G6PC2), glucokinase (GCK) and glucokinase regulatory protein (GCKR) as candidate genes for type 2 diabetes (T2D) acting through elevated fasting plasma glucose (FPG)." (PMID 20628598, 2010).
diabetes (45 papers, 2010 to 2025). "PPI analysis revealed MTNR1B’s strong association with diabetes, obesity, cancer, and circadian rhythm disorders, collectively known as circadian syndrome, and MTNR1B’s close interaction with thermogenic genes (UCP1, PPARG, and PPARGC1A)." (PMID 40697662, 2025). "In conclusion, we demonstrate that diabetes-associated genetic variation in MTNR1B can raise glucose concentrations through α-cell dysfunction in addition to having effects on insulin secretion." (PMID 39011323, 2024). "We therefore used our database to compare subjects homozygous for the diabetes-protective allele (CC at rs10830963) with those having 1 or 2 copies of the diabetes-associated allele (CG/GG at rs10830963) in MTNR1B." (PMID 39011323, 2024). "Carriers of the minor G-allele of the MTNR1B rs10830963 snp represent a large part of populations that have elevated fasting glucose and higher risks of metabolic disorders, particularly type 2 diabetes mellitus." (PMID 38248453, 2023). "A commonly studied polymorphism of the MTNR1B gene is rs108390963, which is associated with an increased risk of diabetes." (PMID 37511203, 2023). "Studies have shown that melatonin inhibited the secretion of insulin from pancreatic β-cells through the melatonin receptor 1b gene, thereby increasing blood sugar levels and increasing the risk of diabetes." (PMID 37310940, 2023). "Given that both extreme chronotype and the MTNR1B risk allele increase the risk of diabetes 7, 9, it is important to study their possible interaction in large cohorts, whilst adjusting for potential confounders." (PMID 31623012, 2020). "Collectively, whereas the previous study showed an association between late chronotype and diabetes, here we further demonstrate a specific risk of late chronotype and MTNR1B genotype with T2D." (PMID 31623012, 2020). "In the context of metabolic syndrome, melatonin secretion levels are low in patients with insulin resistance and impaired glucose tolerance, and mutations in MTNR1B gene are associated with an increased risk of diabetes." (PMID 30037127, 2018). "It has been demonstrated that MTNR1B gene polymorphisms are associated with features of metabolic syndrome, including diabetes." (PMID 29156748, 2017). "Together with previous reports of associations between fasting glucose/diabetes and the MTNR1B and CRY2 loci, our data support a role for the circadian clock in the regulation of glucose homeostasis." (PMID 22485135, 2012). "However, MTNR1A and RORA are not included in the main disease cluster studied, showing that MTNR1B, among melatonin receptors, has a stronger association to metabolic diseases such as obesity and diabetes." (PMID 40697662, 2025). "A previous meta-analysis combined data from 10 GWASs of individuals of European ancestry free of diabetes that validated the appreciable associations between several variant loci (rs1387153, rs11020107 and rs10830963) of MTNR1B and fasting glucose levels as well as reduced β-cell function." (PMID 36974476, 2023). "The MTNR1B rs10830963 G allele is also associated with disturbed circadian phenotypes and altered melatonin secretion, both factors that can elevate the risk of diabetes." (PMID 36974476, 2023). "The connection between “low birth weight and high risk of diabetes” was proposed by the thrifty gene hypothesis, which can also help explain the evolutionary scenario of the MTNR1B gene." (PMID 36986139, 2023). "The MTNR1B rs10830963 G-allele may be a link between circadian rhythm alterations, metabolic disorders and diabetes." (PMID 38248453, 2023). "Studies have consistently demonstrated that MTNR1B is a true causal gene for diabetes, but the underlying molecular mechanisms remain unclear." (PMID 36974476, 2023). "A novel approach of associating clinical utility to the crude GWAS findings and the MTNR1B rs10830963 associated genetic effects to distinct endophenotypes within the diabetes mellitus spectrum might demonstrate consistently similar features." (PMID 32373162, 2020).